CAT (catalase)
Diseases named in the same sentence as CAT in open-access papers (continued):
Sharing a sentence is not in itself a finding about the gene and the disease.
atherosclerosis (50 papers, 2010 to 2026). A disease characterized by the build-up of fatty material and calcium deposition in the arterial wall resulting in partial or complete occlusion of the arterial lumen. "The weakening of the antioxidant defense system of the body, as evidenced by a decrease in catalase activity and the serum ceruloplasmin level, and an increased risk of atherosclerosis due to the hypoalphacholesterolemia were demonstrated." (PMID 38108959, 2024). "Another study shows that overexpression of Cu/Zn-SOD and/or catalase in ApoE-deficient mice suppresses benzo (a) pyrene-accelerated atherosclerosis." (PMID 21600015, 2011). "The shortest way in CTPDN mainly divided into three types, AKT1, lipid and atherosclerosis, CAT and chemical carcinogenesis—receptor activation, and AKT1 or HMOX1 with STAT1 together acting on fluid shear stress and atherosclerosis." (PMID 40217538, 2025). "The inhibited expression and activity of catalase at the transcriptional level was revealed in the pathological environment of atherosclerosis." (PMID 38502586, 2024). "Recent studies have found that tanshinone IIA prevents oxidative stress by increasing the activities of total antioxidant capacity (T-AOC), SOD, glutathione peroxidase (GSH-Px), and catalase (CAT) to reduce atherosclerosis." (PMID 38136596, 2023). "Under oxidative stress, the content of antioxidant molecules such as SOD and CAT will decrease, directly damaging the vascular endothelium and inducing inflammation, thereby promoting the progression of atherosclerosis." (PMID 35571088, 2022). "The key pathophysiological role of GPx, SOD, and catalase in human atherosclerosis was highlighted in a systematic review and meta-analysis of 3 cohort and 41 case–control studies." (PMID 34829712, 2021). "In our study, the increased level of CAT was directly related to the content of octadecenoic acid (C 18:1) in the group of patients with atherosclerosis." (PMID 34945751, 2021). "This, in combination with an impaired function of key antioxidant systems that include GPx, SOD, and catalase, promotes oxidative stress and, consequently, the development of endothelial dysfunction, vascular damage, and atherosclerosis." (PMID 34829712, 2021). "In the vascular wall, oxidative stress is counteracted by several antioxidant enzyme systems including SOD1 and CAT; indeed, in ApoE KO mice, the overexpression of both genes reduced atherosclerosis." (PMID 32824091, 2020). "Nevertheless, overexpression of catalase in ApoE−/− mice results in the retardation of atherosclerosis." (PMID 23442817, 2013). "For example, ApoE null mice have lower serum apolipoprotein E and develop significant early atherosclerosis but overexpression of catalase, an important antioxidative defense, appears to confer protection against early atherosclerosis." (PMID 21490698, 2010). "Moreover, it promotes the activation of the Nrf2 pathway, resulting in an upregulation of the antioxidant enzymes SOD, CAT, and GPx, studied in high-fat diet–induced atherosclerosis in the carotid artery of rats, where a dose of 30 mg/kg/day of QRC was used." (PMID 41228388, 2025). "Increased ROS impair the function of antioxidant system enzymes, such as superoxide dismutase, glutathione peroxidase, and catalase, further contributing to OxS and the development of vascular inflammation, endothelial dysfunction, and atherosclerosis over the long term." (PMID 37653931, 2023). "Overexpression of catalase slows the progression of atherosclerosis in ApoE−/− mice." (PMID 36497101, 2022). "Furthermore, myeloid deletion of NRF2 reduces catalase expression, and increases inflammation and atherosclerosis." (PMID 36497101, 2022). "Indeed, data obtained in vitro highlight the ability of polyphenols to reduce the inactivation of catalase (CAT) by hypochlorous acid (HOCl); this effect protects against atherosclerosis following LDL oxidation by HOCl through apoB-100 chlorination." (PMID 34209636, 2021).
atherosclerosis (continued). "Its strong antioxidant properties are due to the scavenging of radicals and the stimulation of synthesis and activity of antioxidant enzymes (SOD, CAT, HO-1, NOS, COX-2, GSH), which also limit the lipid peroxidation of low-density lipoprotein (LDL) cholesterol, a hallmark of atherosclerosis." (PMID 32825589, 2020). "In apoE-/- mice, overexpression of both SOD1 and catalase, which can degrade hydrogen peroxide, reduced atherosclerosis, while overexpression of SOD1 alone, on the contrary, could enhance the pathology development." (PMID 32245238, 2020). "It was observed that reduced expression of CAT can induce atherosclerosis onset and progression." (PMID 30050655, 2018). "Reduced glutathione (GSH), catalase, and superoxide dismutase (SOD) are significant defensive antioxidants that scavenge oxygen free radicals and thus defend against atherosclerosis." (PMID 37241788, 2023). "Pathological tests (oil red O, HE, and Masson staining) combined with biochemical indices (TC, TG, LDL-C, HDL-C, TNF-α, hs-CRP, NO, SOD, MDA, CAT, and GSH-Px) were performed to evaluate the pathological degree of atherosclerosis in each group." (PMID 36180828, 2022). "Accordingly, aged LDL receptor knockout mice transplanted with bone marrow that overexpresses mitochondrial catalase to reduce mitochondrial H2O2 production, presented with less atherosclerosis compared to mice transplanted with wild-type bone marrow." (PMID 36139808, 2022). "BA also inhibits oxidative stress to alleviate the development of atherosclerosis by decreasing the level of MDA and enhancing the levels of SOD, CAT, and GSH-Px." (PMID 35059326, 2021). "In this context, in atherosclerosis, it has been shown that genistein restrains ROS and MDA production, and ameliorates the inhibitory effect on SOD, CAT, glutathione (GSH), and glutathione peroxidase (GPx) activity elicited by ox-LDL stimulation." (PMID 29973576, 2018). "Yang H., Roberts L.J., Shi M.J., Zhou L.C., Ballard B.R., RichardsonA., Guo Z.M. Retardation of atherosclerosis by overexpressionof catalase or both Cu/Zn-superoxide dismutase and catalase inmice lacking apolipoprotein E. Circ." (PMID 39722671, 2024). "Turmeric improves serum SOD and CAT activity; inhibits the production of inflammatory molecules, such as TNF-α, IL-6, COX-2, and 5-LOX; prevents endothelial dysfunction; and suppresses cholesterol accumulation in macrophage foam cells and atherosclerosis." (PMID 37241765, 2023). "For CAT and SOD, since oxidative stress and hypoxia additively or synergistically exacerbate greater atherosclerosis, the increase in antioxidant enzyme activity may reduce free-radical-induced damage, and provide protection against neurological injury." (PMID 37731856, 2023). "These recognized atherosclerosis-fighting enzymes include SOD, GPx, GR, CAT, and PON-1." (PMID 36422550, 2022). "In our study, the increased aortic MDA level along with the decreased SOD, CAT, GPx, GST, and GR activities, as well as decreased TAC and GSH levels in the OB group, suggests the presence of oxidative stress, which can accelerate the progress of atherosclerosis." (PMID 33562069, 2021). "Indeed, SOD1 overexpression alone may increase the extent of atherosclerosis; however, overexpression of catalase, in addition to SOD1, reduces atherosclerosis in ApoE−/− mice." (PMID 31354915, 2019). "The upregulation of SOD1, CAT, MIF, and PPARγ observed in this study is in line with previous works, which have demonstrated the antioxidant proprieties of a diet rich in nuts, related to the regulation of cellular pathways of atherosclerosis, inflammation, and oxidative stress." (PMID 31354906, 2019).
melanoma (47 papers, 2009 to 2025). A malignant, usually aggressive tumor composed of atypical, neoplastic melanocytes. "In contrast to dacarbazine, which caused a lowering of CAT activity in both types of melanoma cells." (PMID 37195561, 2023). "Mutations in the CAT gene were found in 10% of the melanoma patients, mostly leading to increased mRNA expression, but these mutations had no significant impact on survival." (PMID 37297001, 2023). "Our analysis demonstrated that 10% of the melanoma patients have the mutation on the CAT gene and the most common was increased mRNA expression." (PMID 35326089, 2022). "The nuclear increase of p27Kip1 in melanoma cells either overexpressing or treated with catalase was associated with a decrease in the levels of the phosphorylated protein at S10 and T198." (PMID 22970236, 2012). "A significant G1 cell cycle arrest was found associated with the inhibition of cell proliferation in melanoma cells treated with catalase for 24 h." (PMID 22970236, 2012). "The associated increased catalase activity occurs, for example, in melanoma or glioblastoma." (PMID 38068888, 2023). "Therefore, considering that H2O2 inhibits TYR, TYRP1 and TYRP2, the high levels of H2O2 associated with low catalase activity in melanoma would be relevant in the induction of the amelanotic phenotype." (PMID 27206672, 2016). "First, we found that treatment of patient-derived melanoma CTCs with hydrogen peroxide (H2O2) (0–25 μM)—a major component of ROS—caused a dose-dependent increase of NRF2 target gene expression along with downstream anti-oxidant CAT, GSS, and TXNRD1 effector genes." (PMID 31003475, 2019). "However, H2O2 is also able to regulate the cellular localization of p27Kip1 in transformed melanocytes, since melanoma cells overexpressing or treated with exogenous catalase exhibit a high percentage of p27Kip1 positive nuclei, as compared with melanoma cells deficient in catalase." (PMID 26064422, 2015). "In one trial, catalase-loaded nanoparticles combined with anti-PD-1 therapy for advanced melanoma led to enhanced T cell infiltration and improved overall response rates compared to anti-PD-1 monotherapy." (PMID 41048631, 2025). "In a murine model of melanoma, tumors treated with catalase-loaded nanoparticles exhibited significantly higher levels of T cell infiltration compared to untreated controls, resulting in reduced tumor growth." (PMID 41048631, 2025). "For instance, catalase-loaded nanoparticles used alongside anti-PD-1 therapy have been shown to significantly enhance tumor regression in preclinical models of melanoma." (PMID 41048631, 2025). "α-MSH-mediated oxidative stress and lipid peroxidation are attenuated by treatment with CC-EO or cinnamaldehyde through the regulation of GSH level and CAT activity in α-MSH-induced B16 melanoma." (PMID 38791435, 2024). "In melanoma, there appears to be a redox imbalance characterized by decreased catalase activity and increased SOD activity." (PMID 37297001, 2023). "Data from the Gene Expression Omnibus database also show that three ethanol metabolizing enzymes (alcohol dehydrogenase 1B, P450 2E1, and catalase) and an AcAH metabolizing enzyme (aldehyde dehydrogenase 2) are significantly reduced in melanoma tissues." (PMID 36831600, 2023). "A microarray in melanoma cells with different ROS levels after overexpression of catalase showed that dissimilar phenotypes were generated by differential compensation to hydrogen peroxide scavenging." (PMID 35326089, 2022). "For instance, enzymes glucose oxidase (GOx) and catalase (CAT) were used as components to a microneedle (MN) patch for a minimally invasive transdermal melanoma treatment." (PMID 35049657, 2022). "Significant overexpression of CAT has also been observed in human melanoma biopsy samples, colon cancer tissue, and gastric carcinoma cells." (PMID 34943091, 2021).
melanoma (continued). "Specifically, the downregulation of CAT expression has been shown in pancreatic cancer cells and mouse skin tumors, but upregulation of CAT expression has been reported in melanoma, colon cancer, gastric adenocarcinoma, and GBM cells." (PMID 34943091, 2021). "The extract of SIFs inhibited the oxidative stress and lipid peroxidation of A375 melanoma cells by increasing CAT, SOD, and GPX activities." (PMID 31941038, 2020). "While CNP lowered the viability of the tumor cells to approximately 50%, PEG-catalase preincubation alone increased cell viability compared to control and fully rescued the melanoma cells from CNP-induced toxicity." (PMID 31951630, 2020). "Prior to incubation with 300 μM nanoceria for 96 h, the A375 melanoma cells were incubated for 4 h with catalase (5000 U/ml) coupled to methoxy-polyethylene glycol (PEG)." (PMID 31951630, 2020). "The induced toxicity was abrogated by prior addition of catalase (1000 units/ml) indicating exogenous H2O2 being important to synergize with CcO inhibition in melanoma cell death." (PMID 30143716, 2018). "Melanoma cells exhibit high levels of such reactive species and often reduced expression of catalase, glutathione-S-transferase, or manganese-dependent superoxide dismutase (MnSOD) activity." (PMID 30143716, 2018). "Catalase overexpression on human amelanotic melanoma A375 cells gave rise to a clone with increased polarity related to differentiated melanoma (A7), and another clone (G10) with disrupted polarity associated with malignant progression (in press, 2016)." (PMID 27206673, 2016). "This work demonstrated a differential response of the AOS network induced by catalase overexpression in A375 melanoma cells." (PMID 27206673, 2016). "This work shows that overexpression of catalase in A375 melanoma cells inhibits proliferation in agreement with previous results." (PMID 27206672, 2016). "In this study, a differential compensation to H2O2 scavenging by catalase overexpression in A375 amelanotic melanoma cells was demonstrated." (PMID 27206672, 2016). "Considering that H2O2 scavenging inhibits cell proliferation, we propose herein that melanoma cells triggered different responses to reach a redox homeostasis overcoming the effects on survival induced by catalase." (PMID 27206672, 2016). "This work presents a melanoma cell model with low levels of H2O2 induced by catalase overexpression to study differentiation/dedifferentiation processes." (PMID 27206672, 2016). "Gene expression microarrays in A375 melanoma cells with different ROS levels after overexpressing catalase were performed." (PMID 27206673, 2016). "In order to confirm the effects of H2O2 scavenging on p27Kip1 localization observed by immunofluorescence, the levels of this protein in nuclear and cytosolic extracts of melanoma cells treated with catalase were evaluated by western blot." (PMID 22970236, 2012). "We validated our model of melanoma cells treated with catalase added to the culture medium by measuring the decrease in the levels of ROS through 2′, 7′-dichlorodihydro-fluorescein diacetate (DCFH-DA) assay." (PMID 22970236, 2012). "The other human cancer cells, derived from colorectal carcinoma and neuroblastoma, used in our study, showed a similar response to catalase treatment, extending the results observed for melanoma cells." (PMID 22970236, 2012). "Remarkably, p27Kip1 was localized primarily within the nucleus in melanoma cells treated with or overexpressing catalase as compared with controls, in which p27Kip1 distribution was predominantly cytoplasmic." (PMID 22970236, 2012). "In order to extend the results observed for melanoma cells treated with catalase to other human cancer cell types, we evaluated cell proliferation, cell cycle and p27Kip1 intracellular distribution in colorectal carcinoma (LoVo) and neuroblastoma (Paju) cells." (PMID 22970236, 2012).
melanoma (continued). "In addition, we investigated survival in the TCGA melanoma dataset, as tRNA-iMet-CAT transgenes were shown to promote the metastasis of melanoma cells in mice." (PMID 37509247, 2023). "Compared to CHO cells, melanoma cells presented decreased activities of catalase and SOD." (PMID 35326089, 2022). "Besides, iNOS, SOD1, NOX4, PRX3, PXDN and GPX1 are generally increased during melanoma progression, while CAT, GPX3, TXNIP and PRX2 are decreased." (PMID 35326089, 2022). "On the one hand, it was shown that catalase overexpression correlated with regression of melanoma malignancy and that its downregulation could favor malignant progression." (PMID 34943045, 2021). "Investigations have also reported that administration of myricetin in combination with other antioxidants such as vitamins C or E in murine melanoma B16F10 cells can induce increased catalase (CAT) activity and decrease superoxide dismutase (SOD) and glutathione peroxidase (GPx) activities." (PMID 32962067, 2020). "Therefore, to overcome the inhibition of cell proliferation induced by catalase overexpression, cells changed the redox status leading to distinct phenotypes ranging from reversion to promotion of melanoma malignancy." (PMID 27206672, 2016). "Thus, to identify genes involved in melanoma progression or regression after an AOS response, we developed a human melanoma model with different levels of ROS by stably overexpressing catalase in A375 cells (in press, 2016)." (PMID 27206673, 2016). "Then, to examine whether BMP-4 suppresses the promoter activity of PKC-β, a PKC-β promoter-CAT reporter construct was transfected into paired cultures of LH melanoma cells." (PMID 20130821, 2009). "Moreover, the lower relative intracellular H2O2 content in the CCPC (30.6%) and CCPCA (27.4%) groups also demonstrated the in vitro catalytic activity of CAT in human A375 melanoma cells, suggesting sufficient in situ O2 generation ability to alleviate tumor hypoxia." (PMID 36266306, 2022). "The fact that preincubation with PEG-catalase fully rescued melanoma viability further promotes our hypothesis that nanoceria increase the intracellular concentration of H2O2 exceeding a critical threshold and finally lead to changes in mitochondrial homeostasis with subsequent cell death." (PMID 31951630, 2020). "Moreover, the PPE is reported to induce genes encoding antioxidative enzymes (SOD and catalase) in the B16 mice melanoma cell line, although the molecules responsible have not been identified." (PMID 29599925, 2018). "We found some evidence of GxE interactions with sun exposure, notably, with MC1R, CAT and NOS1 genes in melanoma, HAL and IL23A in BCC and HAL and XRCC1 in SCC." (PMID 37537768, 2023). "In melanotic melanoma cells, sulindac increased the activity of SOD and the content of H2O2 but decreased the activity of CAT and GPx." (PMID 37195561, 2023). "Upregulation of additional genes from the bile acid and peroxisome signaling pathways was also evident in TIL gene and pathway expression analysis, including upregulation of SOD1, ACSL5, FADS2, CAT, DHCR24, SLC27A2, and IDH2 in melanoma TILs compared to pCD8s." (PMID 38023136, 2023). "Most notably, with MC1R, CAT and NOS1 genes in melanoma, HAL and IL23A genes in BCC and HAL and XRCC1 genes in SCC." (PMID 37537768, 2023). "The master stress response transcription factor Nrf2, which regulates the expression of antioxidant enzymes such as HO-1, SOD, CAT, and GPX, is primarily responsible for redox homeostasis in melanoma." (PMID 36747120, 2023). "When compared to normal skin tissues, primary melanoma tissues showed reduced ADH1B, CYP2E1, and CAT gene expression in at least two of three datasets (left), consistent with previous observations for ADH1B." (PMID 36831600, 2023). "Once catalase was shown to play a crucial role in melanoma, some studies using the cell-permeant polyethylene glycol conjugated catalase (PEG-catalase) have been published." (PMID 35326089, 2022).